IRF7 (interferon regulatory factor 7)
Diseases named in the same sentence as IRF7 in open-access papers (continued):
Sharing a sentence is not in itself a finding about the gene and the disease.
autoimmune disease (continued). "In the context of autoimmune diseases, the ubiquitination of the cGAS-STING pathway can interact with IRF3/IRF7." (PMID 40028324, 2025). "With a diverse array of functions, IRF7 was a pivotal component in the type I/III IFNs induced signaling pathway, contributing significantly to viral infections, autoimmune diseases, and the maintenance of homeostasis." (PMID 38999981, 2024). "Combined with the control of the nuclear translocation of IRF7, the modulation of STAT1 transcription and phosphorylation, Bank1 contributes to IgG production during development of autoimmune disease." (PMID 27228057, 2016). "The interferon response is tightly regulated to ensure proper clearance of pathogens without inducing autoimmune disease or excessive tissue damage, and the transcription factor IRF7 is considered the master regulator of the Type-1 interferon response." (PMID 24994117, 2014). "Although it is unclear at present how IKKα links to IRAK1, either kinase appears to be the gateway for activation of IRF7 to induce IFN-α production in pDCs and both could be potential targets for the treatment of autoimmune disorders." (PMID 20470398, 2010). "Given a recent study showing that the activation of IRF7 depends on an IKK subfamily IKKα at the downstream of the TLR7/9-MyD88 pathway in pDCs, IKKα would be a potential molecular target for the treatment of type I IFN-related autoimmune diseases." (PMID 20470398, 2010). "In addition to directly regulating pDC type I IFN responses through IRF7, EBI2 may also influence pDC responses by guiding their migration to and localization within lymphoid tissues or, in the case of autoimmune diseases, target organs." (PMID 24386204, 2013).
Obesity (17 papers, 2014 to 2025). Accumulation of substantial excess body fat. "The gene IRF7 (Interferon Regulatory Factor 7) is associated with the pathogenesis of lung cancer, type 1 diabetes, and obesity." (PMID 39024368, 2024). "In mice, thermogenic fat cells were naturally deficient in IRF7, while, in humans, obesity increased the level of adipocyte IRF7." (PMID 36443525, 2022). "Diet-induced obesity in mice and obesity in children were associated with robust expression of genes encoding IRF7-associated pathways." (PMID 36443525, 2022). "Contrary to CRACR2B, evidence for a direct association between IRF7 and obesity have been shown with IRF7 knockout mouse being protected from gain weight after high-fat diet exposure." (PMID 30452450, 2018). "Type I IFNs have previously been indirectly implicated in obesity development based on the analysis of the IRF-7−/− mouse." (PMID 28660492, 2017). "IRF7 deficiency can prevent diet-induced obesity and insulin resistance." (PMID 40951426, 2025). "We confirmed that sterile inflammation is the underlying cause of diabetes and obesity in db/db mice and showed that the activation of the cGas-STING pathway and the resulting upregulation of Irf7 takes place as early as at 8 weeks of age." (PMID 37979047, 2024). "Interferon regulatory factor 7 (IRF7) is a member of the interferon regulatory transcription factor family and is involved in the pathogenesis of diabetes, obesity, and lung cancer." (PMID 36685671, 2023). "In turn, suppressing IRF7 expression in adult adipocytes restores mtRNA-induced mitobiogenesis and thermogenesis and eventually mitigates obesity." (PMID 36443525, 2022). "The levels of IRF7-associated ISG-encoding transcripts, including IFI16, ZBP1 and TMEM173 (STING1), were increased in the adipose tissue of children with obesity, reflecting their elevated IRF7 levels." (PMID 36443525, 2022). "IRF3 and IRF7 are key transcription factors regulating ISGs; however, their role in obesity development is conflicting." (PMID 36443525, 2022). "Altogether, these data show that obesity is linked to deficient VDR signalling, which is further associated with increased IRF7 expression." (PMID 36443525, 2022). "More recently, the involvement of IRF7 in the pathogenesis of obesity was related to its capacity to regulate CCL2 expression." (PMID 33430520, 2021). "We revealed the transcription factor IRF7 was involved in the pathogenesis of obesity, presumably by regulating the pro-inflammatory adipokine MCP-1." (PMID 32437400, 2020). "Among them, interferon regulatory factor 7 (IRF7) is a new strategy for the treatment of obesity and type 2 diabetes." (PMID 30521536, 2018). "Moreover, we found that as obesity develops after 12 weeks of age, the activation of Irf7 is muted, possibly to regulate the metabolic response, as loss of Irf7 was shown to decrease glucose tolerance." (PMID 37979047, 2024). "Similarly, diet-induced obesity increased the adipose tissue level of Irf7 and abrogated Vdr expression in mice." (PMID 36443525, 2022). "Adipose tissue expansion and obesity are associated with the activation of STAT1 and NF-κB signalling, which may account for the increase in IRF7 expression during postnatal adipocyte development and in obesity." (PMID 36443525, 2022). "In this regard, it has been shown that deficiency of IRF7, a master regulator of IFN-I induction, prevents high fat diet (HFD)-induced obesity and insulin resistance pointing to the involvement of this factor in diet-induced alterations in energy metabolism and insulin sensitivity." (PMID 33430520, 2021). "Taken together, our results suggest that IRF7 transactivates MCP-1 mRNA in adipocytes, and it may be involved in the adipose tissue inflammation associated with obesity." (PMID 32437400, 2020). "Due to the tight correlation between inflammatory response and obesity, IRF7 may appear as a better candidate to link rs35694355 with disease sensitivity." (PMID 30452450, 2018).
Obesity (continued). "IRF7 has also been shown to contribute to diet-induced obesity and insulin resistance." (PMID 25938420, 2015). "Irf7 is the only KD for XYM, which has been recently suggested to be a TF in adipocytes with roles in adipose tissue immunity as well as obesity." (PMID 35396276, 2022). "We were unable to estimate the physiological importance of IRF7 in hypertrophy-mediated MCP-1 induction in fat cells, because of the strong resistance to obesity in knockout mice." (PMID 32437400, 2020). "Both IRF3 and IRF7 are involved in the induction of IFN-I production, which has also been reported to play an important role in obesity-mediated metabolic syndromes." (PMID 33574823, 2020). "In turn, when we inhibited IRF7 expression with VDR activation and transfected adipocytes with mtRNA, we could effectively induce beige adipogenesis and mitigate obesity in mice." (PMID 36443525, 2022). "In children, the adipose tissue level of IRF7 mRNA was strongly increased by overweight and obesity (body mass index standard deviation score over 1.28), while the level of IRF3 mRNA was unrelated to obesity status." (PMID 36443525, 2022). "Interferon regulatory factor 7 (IRF7) is identified as a novel cardiovascular stress inducer in pathologically stressed hearts and involved in the etiology of metabolic disorders, which becoming a new strategy for the treatment of obesity and type 2 diabetes." (PMID 30521536, 2018). "Physiologically, IRF7 may be activated through increased endotoxemia in the absence of apparent obesity, and it may be involved in the early induction of MCP-1 in adipose tissues." (PMID 32437400, 2020). "Furthermore, interferon regulatory factor 7 (IRF-7) was found to be a positive regulator of weight gain in a murine model, suggesting an obesity-related negative feedback cycle, depending on the interferon pathway." (PMID 25093191, 2014).
asthma (16 papers, 2016 to 2024). "Further evaluations showed that the GRB2 gene in both COPD and MLD and the ESR1 and IRF7 genes in asthma and IPF had the highest association with the other genes, respectively." (PMID 37422662, 2023). "Immune transcriptome analysis of LNR125 treated BECs from individuals with asthma indicated that blocking IL-25 restored antiviral immunity with evidence of upregulation of ISGs, such as IRF7 and TBK1 and interleukin-1 receptor-associated kinase 2 (IRAK2)." (PMID 35508632, 2022). "Distinct IRF7-associated asthma risk immunophenotypes have dichotomous responses to virus/allergen coexposure and respond differentially to OM-85 pretreatment." (PMID 34367159, 2021). "In a recent landmark paper comparing asthma risk in Amish (low risk) and Hutterite (4x higher risk) farm children, IRF7 was identified as a differentially expressed hub gene." (PMID 32658914, 2020). "MiR-30b-5p, originating from M2 macrophage exosomes, has the ability to inhibit pyroptosis in airway epithelial cells, thereby improving the progression of asthma through its targeting of IRF7." (PMID 38671352, 2024). "ILC2 from asthma patients have shown higher level of IRF7 than those from healthy donors and IRF7 expression was also reported in murine lung ILC2 upon papain or IL-33 stimulation." (PMID 36506643, 2022). "Defects in TLR7/interferon regulatory factor 7 (IRF7) signaling predisposes to severe viral bronchiolitis and subsequent asthma." (PMID 29065558, 2017). "Employing a computational analysis of gene expression profiling data derived from nasal wash samples, we also showed that IRF7 was a major hub, connecting interferon-related gene networks during picornavirus-induced asthma exacerbations in children." (PMID 26810609, 2016). "ILC2s from asthma patients display a markedly higher level of IRF7 than those from healthy donors, indicating that IRF7 might enhance the development of asthma." (PMID 37251373, 2023). "To explore the role of IRF7 gene networks in children with more severe disease, we profiled gene expression in nasal swab samples from children (<17 years old) who presented to the emergency department with severe exacerbations of asthma or wheeze." (PMID 32887352, 2020). "Moreover, employing cluster analysis of gene expression profiles we demonstrated that immune response patterns during acute exacerbations of asthma/wheeze were highly heterogeneous and could be divided into IRF7-high versus IRF7-low molecular phenotypes." (PMID 34945765, 2021). "To investigate this, we treated IRF7-/- mice with anti-HMGB1 (clone 2G7), which neutralises both all-thiol and disulphide HMGB1, or an isotype-matched control, then killed the mice at 10 dpi when the pathologies associated with asthma onset were most prominent." (PMID 32658914, 2020). "However, by using IRF7-/- mice, we do not presume that our findings are relevant to all cases of viral bronchiolitis in infancy; indeed we agree with view that there are different endotypes of bronchiolitis, as is now accepted to be the case for asthma." (PMID 32658914, 2020).
melanoma (16 papers, 2013 to 2026). A malignant, usually aggressive tumor composed of atypical, neoplastic melanocytes. "However, the incidence of IRF7 mutations is the highest in melanoma among 19 types of solid tumors." (PMID 41535256, 2026). "NOS1 overexpression significantly inhibited IFNB1 and IRF7 transcription in A375 melanoma cells in response to Poly(I:C) stimulation, and this inhibition was reversed by NOS1-knockout." (PMID 41535256, 2026). "We evaluated the clinical relevance of IRF7 expression in melanoma using data from the TCGA database." (PMID 41535256, 2026). "The nuclear localization of IRF7 was also reduced in NOS1 overexpressing melanoma cells, which was partially reversed by high-dose Poly(I:C) treatment." (PMID 41535256, 2026). "Our study suggests that NOS1 expression in melanoma characterizes IFN-I signal disorders in response to innate immune stimulation through IRF7 s-nitrosylation." (PMID 41535256, 2026). "In NOS1-overexpressing melanoma cells, we observed a decrease in the level of IRF7 S-nitrosylation in both human IRF7-C481A A375 cells and mouse IRF7-C435A B16F10 cells." (PMID 41535256, 2026). "To validate that C481A in humans and C435 in mice serve as the primary targets for NOS1-mediated nitrosylation, we deleted endogenous IRF7 in melanoma cells and reintroduced alanine-substituted versions (human IRF7-C481A or mouse IRF7-C435A)." (PMID 41535256, 2026). "The expression level of IRF7 was very low in resting melanoma cells, so we upregulated the IRF7 level by treating cells with IFN-α prior to the Poly(I:C) stimulation." (PMID 41535256, 2026). "Our study showed that stable expression of NOS1 in melanoma cells induced dysfunction of IRF7 through S-nitrosylation, thereby completely impairing the type I IFN response of melanoma cells." (PMID 41535256, 2026). "In the mouse lung metastasis model, IRF7 silencing significantly increased the number of B16F10 metastasis nodules and enhanced tumor growth, suggesting that IRF7 contributes to immune activity in melanoma." (PMID 41535256, 2026). "Therefore, the down-regulation of tumor cell antigen presentation appears to be the most important tumor biological function of IRF7-C435A S-nitrosylation induced by NOS1 expression in melanoma cells." (PMID 41535256, 2026). "The mRNA level of IRF7 is higher in melanoma compared to normal control tissues." (PMID 41535256, 2026). "In this study, we investigated the role of NOS1 expression in regulating IRF7 function by S-nitrosylation regulation, and found that NOS1 induces IRF7 S-nitrosylation, which inhibits the activation of type I IFNs signal in melanoma, leading to the formation of an immunosuppressive microenvironment." (PMID 41535256, 2026). "In this study, it is elucidated that RT can induce the abscopal effect in melanoma by utilizing tumor‐derived exosomes to activate the circPIK3R3/miR‐872‐3p/IRF7 pathway in macrophages, which stimulates the IFN secretion, enhancing the anti‐tumor immune response of CD8+ T cells." (PMID 38286661, 2024). "We observed elevated IRF7 expression in macrophages co‐cultured with irradiated melanoma cells." (PMID 38286661, 2024). "In addition, the expression and activation of IRF3 and IRF7 proteins was enhanced in melanoma cells with NGLY1 knockdown." (PMID 30385822, 2018). "However, since partitioning into two equally sized groups was arbitrary, we determined the optimal grouping for ISG expression in SKCM melanomas by subjecting them to hierarchical clustering according to expression of IRF7.mod." (PMID 25314013, 2014). "Other studies have reported an immune-evasion signature dependent on IRF7 in breast and melanoma." (PMID 24162015, 2013). "Co-immunoprecipitation experiments showed that Poly(I:C)-induced dimerization of IRF7 and IRF3 was reduced in NOS1 overexpressing melanoma cells." (PMID 41535256, 2026). "We assessed the level of IRF7 S-nitrosylation and the impact of NOS1 expression on this modification in melanoma cells." (PMID 41535256, 2026).
melanoma (continued). "In conclusion, our study elucidates the role of exosomal circPIK3R3 in regulating the macrophage IRF7/I‐IFN axis, thereby enhancing the abscopal effects of radiotherapy in melanoma." (PMID 38286661, 2024). "The 12 TFs that were inferred to regulate NK and T cells activation in these modules are shown as follows: Module M1 contained the regulators IRF1, STAT1, SPI1, FLI1, IRF7, and E2F1, which are essential regulators for C4 Melanoma CORO1A." (PMID 37435067, 2023). "In this study, we found that a small amount of IRF7 in resting tumor cells can be modified by NOS1-mediated S-nitrosylation, thereby inhibiting IRF7-mediated transcription of IFNB1, resulting in impaired activation of the type I IFN signaling in melanoma cells." (PMID 41535256, 2026). "Notably, in melanoma cells with NOS1 overexpression, the level of IRF7 induced by IFNα is similar to that observed in control cells, which suggests that the JAK/STAT1 pathway remains unaffected by NOS1." (PMID 41535256, 2026). "Notably, this study revealed that after RT, melanoma cells released exosomes containing circPIK3R3, which promoted IRF7 expression and I‐IFN secretion via the miR‐872‐3p/IRF7 axis in macrophages, facilitating the abscopal effect." (PMID 38286661, 2024). "The data presented in this study hint that pDCs impairment in melanoma might result from defective TLR/MyD88-dependent signaling (i.e., IRF7 activation) or from a broad perturbation of their metabolic functions (i.e., glycolysis)." (PMID 38239354, 2023). "qPCR analysis of endogenous gene expression in mouse melanoma cells with Imp1-3 gene knockouts (no cytokine’s treatment) showed an increase of ISGs levels (e.g., Rig-1, Ifi44, Irf7/9, Oas2)." (PMID 37503349, 2023). "However, IRF7 knockdown with small interfering RNA (siRNA) significantly inhibited these inflammatory factors (IL‐1β, TNF‐α, IFN‐α, and IFN‐β), CD80 and CD86 in macrophages co‐cultured with irradiated melanoma cells." (PMID 38286661, 2024). "Moreover, we detected a considerable inhibition of IRF7 constitutive expression in pDCs after their exposure to SN-mel, providing evidence that TLR/MyD88-dependent signaling in pDCs was inhibited by melanoma secretome." (PMID 38239354, 2023). "For instance, RNA-seq analysis of human melanoma COLO829 cells transfected with MITF short hairpin RNA (shRNA) demonstrates an up-regulation of over 17 of the same 55 innate immune DEGs identified in Mitfmi-vga9/+ McSCs, including Ifih1, Ifit3, Irf7, Parp9, and Stat1 (GSE50686)." (PMID 29723194, 2018).